IL6 (interleukin 6)
Diseases named in the same sentence as IL6 in open-access papers (continued):
Sharing a sentence is not in itself a finding about the gene and the disease.
infection (continued). "With the infection mouse model above, we found that EDL933(ΔTir + HA-Tir) induced lower Tnf, Il6, Il12b, and Il1b than EDL933ΔTir, which was nearly reversed by EDL933(ΔTir + Y490F, Y519F) in the colons and spleens." (PMID 31130074, 2019). "In MOPV-infected wild-type mice, IL-6 mRNA levels had similar kinetics with those in STAT-1-/- mice, with downregulation in the liver and spleen tissues during the infection." (PMID 30650607, 2019). "In acute inflammation and infection, leptin levels increase due to the presence of bacterial endotoxins and other signaling cytokines like TNF-a, IL-6, and IL-1b." (PMID 31186010, 2019). "Infection of hPCLS resulted in increased levels of tumor necrosis factor alpha (TNF-α), interleukin-6 (IL-6), and IL-8 in response to the Δpla strain compared to those in response to wild-type Y. pestis at 2 hpi." (PMID 31085709, 2019). "While IL-1α and IL-1β levels in WT and IL-1R−/− mice were similar, levels of IL-6, IL-12p70, IFN–γ, CCL2, CCL3, and CXCL9 were significantly lower in IL-1R−/− mice compared with wild-type mice following infection with P1/7 (p < 0.05)." (PMID 31262357, 2019). "The activity of nuclear factor-kappa B (NFκB) and the expression of its target gene IL-6 were suppressed in SOCS3-knockdown A549 cells and the TG mice after infection with IAV." (PMID 31474976, 2019). "Infection of murine bone marrow-derived macrophages (BMDMs) with TIGR4 strains demonstrated that macrophage TNF and IL-6 responses to S. pneumoniae were, as expected, highly dependent on TLR2." (PMID 31551336, 2019). "After 14 days of infection (9 days of PMN depletion), the levels of IFN-γ decreased, but the regulatory interleukin 10 (IL-10) and other cytokines, such as IL-12 and IL-6, significantly increased." (PMID 30804100, 2019). "As shown, both TNFAIP3-KO cell clones (KO#20 and KO#03) showed significant higher levels of proinflammatory factors like TNF-α, IL-6, IL-1β, and CCL2 in response to the infection, as compared to that of the wild-type cells." (PMID 31783671, 2019). "Inflammatory induction of hepcidin involves IL-6/STAT3 signaling and is considered to be protective during infection as an innate immune response that deprives bacteria from iron, an essential nutrient." (PMID 31295319, 2019). "Nevertheless, the levels of IL-1β, IL-6, and TNF-α in the HAdV-7 group were higher than the HAdV-3 group post 3, 5, and 7 days of infection (p < 0.01)." (PMID 30626350, 2019). "Consistent with increased cellular recruitment, evaluation of lung homogenates showed an overall increase in TNF, IL-1β, IL-6, IL-17 and KC (CXCL1) in Mtb-LT infected mice at four weeks following infection compared with Mtb-HT infected mice." (PMID 30840702, 2019). "Before infection with E. coli, TNF-α, IL-6, resistin, and leptin contents of the DIO group were significantly higher (p<0.05) than those of the lean group." (PMID 31085802, 2019). "In contrast, infection of SK-N-SH with WNV reportedly results in a sharp increase of key pro-inflammatory cytokines (e.g., IL-1β, IL-6, IL-8, and TNF-α) at day 2 p.i., which coincides with peak virus replication." (PMID 31699097, 2019). "In addition, we examined whether infection led to the induction of proinflammatory cytokines, finding significantly increased transcription of the Tnf-α and Il-6 genes as well as significantly elevated protein levels for IL-1β and IFN-γ as determined by ELISA of cecal protein lysates." (PMID 31848276, 2019). "TSVE moderately up-regulated the mRNA level of IL-6, IL-8, TNF-α, IFN-β, CXCL9 and MX1 over the infection time." (PMID 30866776, 2019). "Previous studies showed low levels of IL-1 in plasma after experimental infection with S. suis, in comparison with other important pro-inflammatory cytokines such as TNF or IL-6." (PMID 31262357, 2019). "The results indicated that the mRNA expression of IL-2, IL-6, and TNF-α induced by Salmonella CVCC541 infection was significantly inhibited after the JH-3 treatment (p < 0.05)." (PMID 30736473, 2019).
infection (continued). "After 72 h infection, the lungs of ΔzipD infected mice showed augmented levels of inflammatory cytokines, including IFN-γ, IL-12 and IL-6, when compared with wild-type and ΔzipD::zipD+ infections." (PMID 31887136, 2019). "In the model, an infection leads to activation of immune cells followed by secretion of pro-inflammatory cytokines, e.g. TNF-α, IL-1β, and IL-6." (PMID 31791247, 2019). "The expression of genes encoding major inflammatory determinants tested including cytokine interleukin-6, complement component C3, and chemokine CCL2 declined from the high levels 15 days after infection to control values 60 days after infection." (PMID 31266862, 2019). "In other models of inflammation and infection, inflammatory cytokines such as IL-1β, TNF, IL-6 and IFN-γ are thought to be the major mediators of DME down-regulation." (PMID 31299982, 2019). "These Th17 cytokines can recruit neutrophils and monocytes to the site of infection or inflammation and lead to the activation of other downstream cytokine and chemokine cascades, such as IL1, IL6, TNF-α, TGF-β, IL8, and MCP-1." (PMID 31089478, 2019). "Defensin 1 administration to macrophages 1 h and 5 h after infection with D39 (MOI10) led to a reduction of bacteria-induced release of key inflammatory cytokines such as IL-1β, IL-6, and TNF-α." (PMID 31657264, 2019). "In this paper we showed that macrophages lacking lincRNA-EPS exhibit increased expression of inflammatory cytokines such as TNF-α, IL-6, IL1-β, and CCL5 upon infection with L. monocytogenes." (PMID 32039056, 2019). "Other investigators found that IL-6 levels were suppressed in human fibroblasts undergoing active infection, mediated in part by HCMV IE2 proteins and post-transcriptional destabilization of IL-6 mRNA." (PMID 30909422, 2019). "On the third day after infection, high levels of proinflammatory cytokines TNF, INF-γ and IL-6 and chemokine MCP-1 were detected in the serum of both infected groups." (PMID 31050676, 2019). "The levels of inflammatory mediators associated with airway inflammation, including IL-1β, TNF-α, IFN-γ, and IL-6, were also clearly elevated in BALF at 3, 5, and 7 days post HAdV-3 and HAdV-7 infection." (PMID 30626350, 2019). "Levels of TNF-α and CCL2 were significantly elevated from pre-clinical to early-stage infection, and IL-6, IL-12b, CCL3, CCL12, and ISG15 levels were significantly elevated from pre-clinical to late-stage infection." (PMID 31790513, 2019). "All serologic tests presented limited values in predicting persisting infection, with the area under ROC curve of ESR, CRP, IL-6 and combination of the three markers was 57.8, 61.6, 60.3, and 62.1%, respectively." (PMID 31159792, 2019). "The dynamic curves of the levels of CRP, IL-6, IL-8, IL-10, SCD163 and TNF-α in both groups demonstrated a similar trend during infection but differences between the groups was observed only in the sTREM-1 levels." (PMID 31387541, 2019). "The infection was associated with limited immune cytokine/chemokine response activation; the highest increase of expression, following infection, was seen in CXCL-10 (IP-10), interleukin-6, 8, 12, and CCL5 (RANTES)." (PMID 29463209, 2018). "Patient ZIKV17 showed concentrations of IP-10, MIG, IL-6, IL-10, INF-γ, IL-8, MCP-1and RANTES higher than control, with the highest values found at the beginning of the infection (p < 0.05), highlighting a local persistent inflammation in the MRS." (PMID 30405055, 2018). "Xiap−/− Treg cells were mostly normal before infection, but were converted into IFN-γ-, IL-6-, and IL-17-expressing T cells in an inflammatory environment." (PMID 29386580, 2018). "During the first weeks of infection, the pro-inflammatory cytokines TNF-α and IL-6 are required for activation of inflammatory cells and for a subsequent efficient Th1 immune response against the parasite." (PMID 29755471, 2018).
infection (continued). "In contrast, another study produced contradictory results to those cited, with higher levels of IL-8, IL-6, and ICAM-1 expression in control cells (CFT1-LCFSN) compared to CF cells (CFT1-ΔF508) after infection." (PMID 30581723, 2018). "Based on our results, the DIO mice showed higher MDA contents, GSH-Px activity, and adipocytokine (leptin, resistin, and IL-6) levels than the lean mice, indicating that DIO mice suffered from high oxidative stress levels before infection." (PMID 30250258, 2018). "At T1, 2 months post-infection, the LM17- and LJL143-immunized dogs presented higher levels of IFN-γ, IL-6, IL-18, CXCL10, GM-CSF, IL-7, IL-15, and CCL2 in comparison to controls." (PMID 30519235, 2018). "In this work, we employed wt and JAK1-expressing LNCaP cells to compare and contrast IL-6 and IFN signaling, in the context of infection with viruses of different oncolytic potential." (PMID 29441069, 2018). "Among the generated mutant strains, different characteristics were observed in the bacterial growth rates and product levels of NO, IL-6, and TNF-α in RAW 264.7 cells responding to infections of C3, C24 and C30 strains." (PMID 30064361, 2018). "The addition of 4 mM VPA to culture medium before infection, significantly induced a 5- and 3-fold reduction in TNF-alpha and IL-6 mRNA expression, respectively." (PMID 29986388, 2018). "A trend toward increased production of IL-6 and IL-17C was detected during infection with ΔpqsA compared to PAO1; this trend became significant in the case of IL-6." (PMID 30619119, 2018). "As revealed by pulmonary cytokine detection, the increase in pulmonary TNF-α, IL-1β, IL-6, and IL-8 levels was more severe in the lean mice than in the DIO mice after infection." (PMID 30250258, 2018). "In M. pneumonia challenged mice, serum IL-6, IL-1β, and TNF-α were significantly higher in mice after 1 month infection than their saline controls." (PMID 29849498, 2018). "The results displayed that mRNA levels of IL-8, IL-6, and TNF-α increased and reached to the peak at 24 h post infection (hpi)." (PMID 30314467, 2018). "After infection of μBS by ZIKV-BR and ZIKV-UG, upregulation of TNF-α, IL6, IL1b, and CCL2 was observed when compared with BS." (PMID 30619100, 2018). "And infection of macrophages with the three ΔsurA/SCV1, Δslp/SCV1, and ΔlpoB/SCV1 mutants led to significantly decreased expression of TLR2, TNF-α, IL-1β, and IL-6 compared with those detected in the SCVs." (PMID 29594069, 2018). "After multiple treatments with insulin, the levels of IL-1β, IL-6, and IFN-γ were increased in the PeLF of diabetic rats after infection with either strain, and CINC-2 levels were restored in N315-infected animals." (PMID 30705678, 2018). "And the mRNA levels of IL-6, IL-8, and CCL-2 in brain tissue were also increased by CA16 infection, and SAM decreased them to some extent." (PMID 30186868, 2018). "In the context of a persistent LCMV infection, it has furthermore been shown that late FDC-derived IL-6 is essential for TFH cell maintenance and eventual control of the infection." (PMID 29887868, 2018). "Here, PKR senses viral RNA at a late time point during infection with HPAIV and provokes TRIM28 S473 phosphorylation via p38 and MSK1 with the consequence of excessive production of IFN-β, IL-6 and IL-8." (PMID 30323812, 2018). "Conversely, in the present study, we observed that mice from both BHIM-Ft sodB and MHM-Ft sodB-immunized groups exhibited low levels of IFN-γ, IL-6, and MCP-1 in the lungs and BALF during the early stage of disease (up to day 10 post-infection)." (PMID 30042767, 2018). "In both infections, we observed an increase in IFN‐γ, TNF‐α, IL‐6, IL‐8, IL‐10, IL‐13, MIP1β, and G‐CSF levels." (PMID 29314720, 2018). "Results from these analyses indicated that GAS induces a 2-fold or greater increase in GM-CSF, IL-1β, IL-6, and MIF in WT vs. mock infection." (PMID 30018884, 2018).
infection (continued). "Concentrations of inflammatory and immunomodulatory cytokines IL-1β, IL-6, TNF-α, IL-10, and IL-13 were significantly greater in BAL samples of Nrf2 KO mice compared to WT controls at day 1 after infection (p < 0.05)." (PMID 29740449, 2018). "(b), (c), (d) Product levels of NO, IL-6, and TNF-α in RAW 264.7 cells responding to infection with each strain (MOI 100) was measured 24 h after infection." (PMID 30064361, 2018). "Increased levels of D-dimer, IL-6, sCD14, CXCL10, TNF-α, IL-18, and CCL2 among others have been shown to be increased during acute infection or chronically increased throughout infection." (PMID 29391069, 2018). "At 4 months after infection (T2), the dogs immunized with either salivary protein presented higher levels of IFN-γ, IL-6, IL-18, GM-CSF, IL-7, IL-15, TNF, and CCL2 when compared to controls." (PMID 30519235, 2018). "Outbred mice also displayed significantly less IL-6, MCP-1, and TNF-α expression throughout infection." (PMID 30533047, 2018). "Infection induces significant cytokine mRNA over-expression (15- and 38-fold for TNF-alpha and IL-6 respectively), which was significantly down-regulated by the TSA treatment until basal non-infected cells level." (PMID 29986388, 2018). "The production of IL-6 showed a profile similar to that of TNF, with upregulation of IL-6 induced by infection in the WT group only in pregnant females." (PMID 29867817, 2018). "In early stage infection, TLR3-/- mice showed a diminished synthesis of IFN-β, IL-1β, and IL-6, but enhanced production of IL-10, TNF-α, and IFN-γ." (PMID 29624589, 2018). "Endothelial cells react to infection with SFGR species by increased expression of cytokines such as IL-1 and IL-6 and chemokines such as IL-8 and MCP-1, which favor the migration of leukocytes." (PMID 29912688, 2018). "Patients who developed VAP also showed a trend to increased levels of the pro-inflammatory mediators IL-6, IL-8 and ICAM-1, reflecting an inflammatory response to infection." (PMID 30283005, 2018). "The expression of IL-6 and TNF-α at initial stages of infection and IL-10 at longer stages was also detected in the serum of mice infected with S. aureus; however, in all these reports, a molecular mechanism was not described." (PMID 29434603, 2018). "At day 6 post-infection, C57BL/6J mice also exhibited higher levels of IL1A, IL1B, CCL2, CCL3, IL2, IL10, and IL6." (PMID 30713529, 2018). "Infection of epithelial cells by strains ATCC 17978 and PAO1 showed that IL-6, tumor necrosis factor alpha (TNF-α), and IL-10 levels were similar for hypoxia and normoxia at 2 and 24 h postinfection." (PMID 30082478, 2018). "Our previous data also showed IL-6 and CCL5 synthesis was diminished during early stages of Cm infection in the genital tract of TLR3-/- mice from a 129S1 genetic background." (PMID 29624589, 2018). "In the context of TC-83 infection, we note that U-87 MG astrocytes produce increased levels of IL-1β, while HMC3 microglia release more IL-1α, IL-1β, IL-6, and IL-8." (PMID 30101649, 2018). "A549 cells were stimulated with medium, 103TCID50 UV-RSV, or 103TCID50 of infectious RSV particles, and IL-6 and IFN-β concentrations in cell culture supernatants were measured by ELISA 36 h post infection." (PMID 29264743, 2018). "Plasma levels of TNF-α, IFN-γ, IL-6, IL-10, CXCL10, CCL2 and IL-4 were all increased upon infection." (PMID 30375380, 2018). "The expression levels of IL‐6 and IL‐17 from NP30‐immunized mice were significantly higher than those of the control in the 4‐week post‐infection group." (PMID 29577333, 2018). "It has been reported that the inflammation is a physiological phenomenon on responding the injury, stress and infection, and the inflammatory mediators of iNOS, COX-2, IL-1β, TNF-α and IL-6 can be increased when ALD occurred clinically." (PMID 29765084, 2018).
infection (continued). "Before infection with E. coli, the DIO groups had significantly higher contents of IL-6, leptin, and resistin but lower content of IL-8 compared with the lean groups (p < 0.05)." (PMID 30250258, 2018). "And infection of macrophages with the three ΔsurA/SCV1, Δslp/SCV1, and ΔlpoB/SCV1 mutants led to significantly decreased expression of TLR2, TNF-α, IL-1β, and IL-6 compared to those detected in the SCVs." (PMID 29594069, 2018). "The levels of plasma adipokines (resistin, leptin, adiponectin), and other markers of inflammation (leukocytes, plasma IL-6, CRP) in the acute phase of Puumala hantavirus infection compared to the recovery phase and one year after the infection." (PMID 30517161, 2018). "IFN-alpha (IFN-α) was detected in the lungs of 6:2 Tky/05 virus-infected mice along with IL-6 at day 2, whereas levels of TNF-α, CXCL1, CCL2 and IFN-γ continued to rise through day 3 post infection." (PMID 29300777, 2018). "Supernatants from cultured macrophages treated with antagomir-HA-3p had lower concentrations of TNF-α, IL-6 and IFN-β than those treated with the control antagomir at 24 and 48 h post-infection." (PMID 29327729, 2018). "In contrast, mb1creIL-4Rα−/lox mice developed significantly increased levels of IL-4, IL-10, IL-6, IL-17, and IFN- γ compared to IL-4Rα−/lox littermate control mice at 24 weeks post infection." (PMID 30619289, 2018). "IL6, IFNB1, CXCL10, and CCL5 gene expression was significantly elevated in ATII cells following infection and was reduced by the addition of apocynin (except for IFNB1)." (PMID 30341336, 2018). "Expression of IL-6 and TNF-α are a potential indicators of severe respiratory viral infection, such as SARS and human infection by avian influenza viruses." (PMID 29566060, 2018). "In contrast, the proinflammatory mediators IL-6 and tumor necrosis factor (TNF) were both significantly increased in sera from Il27ra−/− versus wild-type mice 24 h after Cl13 infection." (PMID 29593047, 2018). "Supernatants from PPD-B stimulated samples were also checked for IL-1β, IL-6, IL-10, IL-12, and TNF-α production over the course of infection using the MSD multiplex platform." (PMID 29343690, 2018). "HeLa cell secretion of IL-6, IL-8, and RANTES into the culture media was analyzed upon infection, irradiation, or the combination of both, and compared to the mock-infected non-irradiated control." (PMID 30524392, 2018). "This minimal induction, which apparently failed to block productive infection in these cells, was potentiated by both IL-6 or IFNα, as 27 or 37 ISGs were induced by the combination of EHDV-TAU infection and these cytokines, respectively." (PMID 29441069, 2018). "Serum concentrations of inflammatory markers, such as interleukin-6 (IL-6) and C-reactive protein (CRP), increase transiently then return to baseline after the infection subsides." (PMID 29198208, 2018). "Some studies have demonstrated the role of the flagellin of P. aeruginosa in induction of IL-6 and TNFα or CXCL8 during mouse infections." (PMID 30070169, 2018). "Similar observations were made at gene expression level; the infection of Mφs led to a significant increase in TNF-α, IL-1β, and IL-6 mRNA levels, and IL-6 mRNA level was further enhanced with IFN-γ addition (p < 0.01)." (PMID 29503646, 2018). "Heightened transcription for IL6 and IL10 in MDSCs despite of lower bacterial replication resulted in more abundant cytokine concentrations in supernatants after 24 h of infection." (PMID 30405617, 2018). "We measured the levels of IL-1β, IL-6, MIP-1α, and CXCL1 in cerebellum and spleen, as well as of bioactive lipids in serum in PEA- and vehicle-treated animals 24 h after infection." (PMID 30505308, 2018).